INS (insulin)
Diseases named in the same sentence as INS in open-access papers (continued):
Sharing a sentence is not in itself a finding about the gene and the disease.
metabolic syndrome (continued). "We have previously found metabolic differences between HIV– and YPHIV in urban Uganda, specifically focused in and around the capital, Kampala, including decreased insulin sensitivity and dyslipidemia in YPHIV versus HIV– in Kampala." (PMID 40799785, 2025). "The underlying mechanisms include chronic systemic inflammation, hepatic insulin resistance with increased hepatic glucose output, endothelial dysfunction, and atherogenic dyslipidemia." (PMID 41104308, 2025). "The DASH diet also improves glycemic control and insulin sensitivity in patients with metabolic syndrome." (PMID 41356834, 2025). "Our data suggest that targeting FFA alone neglects the multiple maladaptive metabolic mechanisms by which the vascular‐insulin resistance homeostasis is been perturbed in metabolic syndrome." (PMID 39888728, 2025). "Chronic low-grade inflammation is a defining characteristic of metabolic syndrome, contributing to dysfunctional insulin signaling, endothelial damage, and lipid imbalances." (PMID 40362807, 2025). "Studies have shown that raw garlic is effective in improving insulin sensitivity and reducing metabolic syndrome and oxidative stress in rats." (PMID 40087612, 2025). "Vitamin D can produce metabolic syndrome by affecting pancreatic β-cell activity and insulin sensitivity, leading to mood disorders such depression." (PMID 40077673, 2025). "Research has shown that AT is associated with reduced fasting insulin levels and Homeostasis Model Assessment (HOMA) scores in overweight and obese children and adolescents, potentially preventing metabolic syndrome and T2DM." (PMID 40136413, 2025). "Numerous investigations have demonstrated the efficacy of short-term VLCD in enhancing insulin sensitivity and addressing various constituents of the metabolic syndrome." (PMID 41458553, 2025). "A crossover clinical trial in subjects with metabolic syndrome (MS) showed that including black beans in a meal had positive effects on the postprandial insulin peak compared to diets similar in fiber and antioxidant capacity." (PMID 39795230, 2025). "In skeletal muscle, the predominant isoform is Cav-3, and its deficiency causes considerable impairment in glucose uptake, which in turn leads to diminished insulin-stimulated signaling, glucose intolerance, and dyslipidemia." (PMID 40358155, 2025). "Visceral fat accumulation exacerbates insulin resistance by secreting adipokines that disrupt glucose homeostasis, while dyslipidemia further compromises insulin sensitivity." (PMID 40332518, 2025). "For instance, daily supplementation with 2 g of Spirulina for 12 weeks significantly improved insulin sensitivity and reduced triglycerides in overweight adults with metabolic syndrome." (PMID 40565730, 2025). "DAG oil has also been proposed as a therapeutic against metabolic syndrome and shown to lower serum insulin." (PMID 40323280, 2025). "This bidirectional connection between lipid abnormalities and insulin resistance creates a reinforcing loop that drives the progression of metabolic syndrome, emphasizing the multifaceted nature of metabolic disturbances in this condition." (PMID 41468519, 2025). "In this context, FMT has emerged as a promising strategy for addressing key components of metabolic syndrome, such as improving insulin sensitivity, body weight and lipid profiles." (PMID 40283508, 2025). "As a key feature of metabolic syndrome, IR reflects the body’s diminished sensitivity to insulin, resulting in disrupted glucose metabolism." (PMID 40275575, 2025). "This is consistent with previous studies in which Mang has improved dyslipidemia, insulin sensitivity, and reverted adipokine levels in a rat model of T2D induced by streptozotocin (STZ)." (PMID 40406487, 2025). "Dysregulation of zinc levels or abnormal zinc transport can influence insulin signaling, oxidative stress, and inflammation, all of which are key factors in the pathogenesis of metabolic syndrome." (PMID 39941463, 2025).
metabolic syndrome (continued). "It is possible that metabolic syndrome increases the amount of circulating insulin-reactive T cell clones, which in turn would exacerbate lymphedema pathology." (PMID 40821816, 2025). "Dyslipidemia, through various pathways, can impair pancreatic function and reduce insulin sensitivity, thereby exacerbating the progression of Pre-DM and DM." (PMID 40530050, 2025). "The Dietary Approaches to Stopping Hypertension (DASH) dietary pattern not only helps to control hypertension but also improves the weight, blood lipids, insulin sensitivity, and blood glucose levels of patients with metabolic syndrome." (PMID 40964683, 2025). "First, to examine if sexual maturation differs in metabolic syndrome between Cyp17a1 KO rats and wild-type rats, we conducted an insulin tolerance test on chow-diet-fed rats at 5, 12, and 20 weeks old." (PMID 41385510, 2025). "PPARγ gene therapy targets PPARγ to improve insulin sensitivity and lipid metabolism in individuals with metabolic syndrome, offering a potential cure for disorders stemming from PPARγ dysfunction." (PMID 40926269, 2025). "Another study explored the effects of supplementing grape pomace (GP) and its extract (GPE) in Wistar rat diet on liver, muscle, and adipose tissues that are insulin sensitive, was conducted using rat model for metabolic syndrome (MetS)." (PMID 38979544, 2024). "In the present study, normal insulin levels during the normal metabolic phases 1 and 2, were associated with normal amylase levels; however, the progression of metabolic syndrome (phases 4 to 6) showed an increase in insulin, but a decline in amylase." (PMID 38955666, 2024). "With an increase in the ALT/AST ratio in Korean men, the following characteristics showed a higher trend: ALT level, AST level, younger age, hypertension, DM, dyslipidemia, alcohol consumption, BMI, WC, insulin levels, Glc levels, HOMA-IR, and HOMA-β." (PMID 38758828, 2024). "In line, the HFCR-I offspring also developed altered glucose and lipid homeostasis by exhibiting impaired glucose tolerance & insulin sensitivity, dyslipidemia and steatosis." (PMID 38851752, 2024). "We altered media components to mimic blood chemistries, including insulin, glucose, free fatty acids, and immune-activating molecules to reflect normal fasting (NF), early metabolic syndrome (EMS), and late metabolic syndrome (LMS) conditions." (PMID 39324073, 2024). "Male gender, dyslipidemia, SU or glinides, insulin and sleeping pills were independently and inversely associated with age of in-hospital death." (PMID 38592103, 2024). "The persistent low-grade inflammation found in metabolic syndrome also plays a role in the development of type 2 diabetes by hindering insulin signaling pathways." (PMID 39574946, 2024). "Body weight, BMI, EW, WC, HC, the prevalence of metabolic syndrome, insulin, and HOMA-IR were notably higher in the biochemical hypogonadal group, while age, LH, and TT values were significantly lower." (PMID 39085709, 2024). "There were significant intergroup differences regarding the type of insulin therapy, presence of sensors, presence of dyslipidemia, and metabolic control between the MD adherence groups." (PMID 38724988, 2024). "Chronic feeding of a high fat diet (HFD) in preclinical species induces broad metabolic dysfunction characterized by body weight gain, hyperinsulinemia, dyslipidemia and impaired insulin sensitivity." (PMID 38825593, 2024). "Early-adiponectin-knockout mouse studies revealed a phenotype of impaired insulin sensitivity after exposure to an HFD, and importantly, it was found that the injection of adiponectin into mice improved insulin sensitivity and dyslipidemia." (PMID 38672492, 2024). "Genetic ablation of miR-33 in hepatocytes improves metabolic function in the liver, enhancing glucose tolerance and insulin sensitivity and attenuating dyslipidemia, steatosis, and MASH." (PMID 39190492, 2024).
metabolic syndrome (continued). "We kept C57Bl6/J mice on a high-fat, high-sucrose (HFHS) diet for 20 weeks and followed biological parameters, including plasma insulin and lipid levels, insulin tolerance, and weight gain, to validate the development of metabolic syndrome." (PMID 38184590, 2024). "Circulating concentrations of phenylalanine and tyrosine are increased in adults suffering from metabolic syndrome (obese states that are insulin-resistant or have T2DM)." (PMID 38892526, 2024). "This can help maintain insulin levels within normal limits and prevent complications related to metabolic syndrome." (PMID 38732523, 2024). "Previous studies have examined diverse aspects of gallstones, exploring their connections with cardiovascular disease, metabolic syndrome, high-calorie intake, and alterations in serum insulin levels." (PMID 38903577, 2024). "The methylation status of these loci was associated with body mass index percentile and showed correlations with several features of metabolic syndrome, including insulin responsiveness, central obesity, fat deposition, and plasma lipid levels." (PMID 39498440, 2024). "Certainly, the transfer of IM from lean, healthy donors to patients with metabolic syndrome through small intestinal injections enhances insulin sensitivity." (PMID 38474087, 2024). "Fetuins are named for their role during fetal development, but research has found that Fetuin B (FETUB) is involved in dyslipidemia, metabolic disease, and insulin signaling in the heart." (PMID 38500750, 2024). "We used RRR to create a dietary pattern to study the connection between dietary insulin indices and nutrients-related dietary pattern with metabolic syndrome in Iranian adults." (PMID 38263222, 2024). "In atherogenic dyslipidemia, impaired insulin signaling increases lipolysis, thereby increasing the conversion from TG into free fatty acids, which then increases VLDL." (PMID 38310558, 2024). "Dietary fish oil can improve or reverse dyslipidemia, adiposity, β-cell dysfunction, insulin secretion, and insulin action on glucose metabolism." (PMID 38414818, 2024). "In this context, SGLT2i, through their modulation of cellular mechanisms, have demonstrated efficacy in improving lipid metabolism, ameliorating dyslipidemia, and enhancing insulin sensitivity." (PMID 39061837, 2024). "Similar findings were obtained in24 a study examining the effects of insulin sensitizers (metformin and pioglitazone) in patients with metabolic syndrome and psoriasis." (PMID 39925996, 2024). "Brown macroalgae supplements have been tested in the management and prevention of metabolic syndrome with promising results such as beneficial effects on insulin levels." (PMID 38799117, 2024). "Fasting insulin has also been used as a screening modality for metabolic syndrome, and metformin has been used as an adjunct for treatment of endometrial hyperplasia." (PMID 39215793, 2024). "The treatment with 4 U/day insulin avoided the dyslipidemia and the increases in biomarkers of glycoxidative stress, with the exception that HbA1c had a slight increase in DI4U rats when compared with the NYOG group." (PMID 38892513, 2024). "The reduction in the prevalence of patients meeting the criteria for metabolic syndrome was significantly greater with pooled tirzepatide doses compared to placebo, semaglutide 1 mg, insulin glargine, and insulin degludec (p < 0.001, all comparisons)." (PMID 38341541, 2024). "Ginsenoside Rb1 (Rb1) oral supplementation ameliorated dyslipidemia, improved insulin sensitivity in HFD-induced obese mice, and reversed the expression of uncoupling protein 2 (UCP2), Nuclear receptor subfamily one group H member 4 (Nr1h4), and Fiaf." (PMID 38469405, 2024). "A recent meta-analysis demonstrated the benefits of combined exercise in overweight/obese T2D patients on dyslipidemia, insulin sensitivity and glycemic control with a great variability in the HbA1c response." (PMID 39633643, 2024).
metabolic syndrome (continued). "Oxidative stress interferes with the ingestion of glucose in the muscles and reduces insulin secretion by pancreatic β-cells, resulting in insulin resistance and ultimately leading to metabolic syndrome." (PMID 38474229, 2024). "Metabolic syndrome’s pathophysiology is characterized by an intricate interplay of metabolic pathways such as insulin signaling, lipid metabolism, glucose regulation, and inflammation." (PMID 38794679, 2024). "It has been reported that TZDs, by their binding to PPAR gamma, modulate the transcription of genes of carbohydrates and lipid metabolism, improving insulin sensitivity, dyslipidemia, adipose tissue remodeling, and adiponectin synthesis." (PMID 39273057, 2024). "Emerging evidence suggests that gut microbiota diversity and composition are associated with reduced risks of metabolic syndrome, a condition characterized by abdominal obesity, dyslipidemia, hypertension, and impaired insulin sensitivity." (PMID 39768329, 2024). "For example, it has been shown that the effect of bread consumption on postprandial insulin response or the influence of vitamin D on markers of the metabolic syndrome differ depending on the individual metabotype." (PMID 38575962, 2024). "By performing a meta-analysis of randomized clinical trials pertaining to metabolic syndrome, Qui, and colleagues report that patients experienced improvement in HbA1c, insulin sensitivity, and HDL cholesterol." (PMID 39452186, 2024). "Diets rich in saturated fats and sugars can worsen dyslipidemia, whereas routine physical activity can enhance lipid levels by boosting insulin sensitivity and facilitating triglyceride removal from the bloodstream." (PMID 39574946, 2024). "This medication can increase insulin sensitivity, decrease weight, and treat dyslipidemia at an early clinical stage, while also dramatically lowering blood sugar levels." (PMID 38987789, 2024). "The activation of inflammatory signaling pathways, such as the nuclear factor kappa B (NF-κB) pathway, inhibits insulin signaling in target tissues such as the liver, skeletal muscle and adipose tissue, resulting in an increase in glycemia and dyslipidemia." (PMID 39728125, 2024). "Reductions in the prevalence of patients meeting the criteria for metabolic syndrome was significantly greater with all tirzepatide doses versus placebo, semaglutide 1 mg, insulin glargine, and insulin degludec (p < 0.001)." (PMID 38341541, 2024). "It ameliorated dyslipidemia, improved insulin sensitivity, and reversed the expression of UCP2, Nr1H4, and Fiaf." (PMID 38469405, 2024). "Curcumin influences multiple aspects of Metabolic Syndrome including insulin sensitivity, blood pressure, inflammation, and abiogenesis suppression." (PMID 39759349, 2024). "In human interventional studies, metabolic syndrome patients showed improved insulin sensitivity after 6 weeks from FMT administration." (PMID 39594528, 2024). "MS dyslipidemia is a consequence of a complex interplay between the inflamed insulin-resistant visceral adipose tissue and insulin-resistant liver, where serum lipases and lipid-transfer proteins play an important role." (PMID 38732266, 2024). "And the function of SCFAs in the regulation of the metabolic syndrome and the maintenance of energy homeostasis and host insulin sensitivity has been confirmed." (PMID 39834378, 2024). "Our results show that fasting FATox is low and the ability to switch between fat and carbohydrate oxidation in response to insulin stimulation is blunted in sedentary and physically inactive adults with metabolic syndrome." (PMID 38416072, 2024). "The adult CMR composite represented key components of adulthood cardiometabolic health measured according to best practices in areas of central adiposity, blood pressure, insulin resistance, inflammation, and dyslipidemia." (PMID 38641792, 2024).
metabolic syndrome (continued). "Concomitant with the reduction in white adipose tissue mass upon ONX-0914 treatment, we observed improvements in markers of metabolic syndrome, including lowered plasma triglyceride levels, insulin levels, and fasting blood glucose." (PMID 38660806, 2024). "The administration of RJ over a 16-week period significantly attenuated final body weight gain, reduced the HOMA-IR index, and mitigated increases in glucose and insulin levels, while also improving dyslipidemia in the HFD-fed rats." (PMID 39339774, 2024). "This implies that individuals with high levels of CAP value should be closely monitored for insulin levels to prevent the onset of metabolic syndrome and other complications." (PMID 38982535, 2024). "In patients with metabolic syndrome, it has been shown that Allo-FMT can result in improved insulin sensitivity, in association with altered gut microbiota composition in both the small and large intestine." (PMID 39200335, 2024). "This is evident from the decreased body weight and fat accumulation, improved glucose tolerance and insulin sensitivity, and correction of dyslipidemia." (PMID 39156823, 2024). "In this post hoc analysis, tirzepatide at all doses studied was associated with a greater reduction in the prevalence of patients meeting the criteria for metabolic syndrome compared to placebo, semaglutide 1 mg, insulin degludec, and insulin glargine." (PMID 38341541, 2024). "A relevant meta-analysis has shown that the HIIT can effectively improve the insulin sensitivity of overweight and obese young people, healthy young woman and adult men with metabolic syndrome." (PMID 39398340, 2024). "Vitamin D plays a significant role in key areas of metabolic syndrome, including insulin sensitivity, lipid metabolism, inflammation reduction, immune response, blood pressure regulation, cardiovascular health, and bone health." (PMID 39183985, 2024). "Fish oil consumption for two months to insulin-resistant rats increased the plasma level of adiponectin and reduced insulin resistance and dyslipidemia." (PMID 37794302, 2024). "Disrupted brain insulin signaling and insulin resistance also play a role in mediating cognitive deficits observed with metabolic syndrome." (PMID 38540695, 2024). "Chromium is an essential mineral that has a beneficial role in regulating insulin action, metabolic syndrome, and cardiovascular disease." (PMID 37132140, 2024). "Further experiments with this bacterium showed that it improved the insulin sensitivity of genetically obese db/db mice, as well as peripheral glycemic control in subjects with metabolic syndrome." (PMID 38542455, 2024). "PCOS syndrome patients are more likely to suffer from insulin cell dysfunction and dyslipidemia, contributing to hypertension." (PMID 38468402, 2024). "Atherogenic dyslipidemia can inhibit insulin metabolism through apoptosis and dysfunction of pancreatic beta cells." (PMID 38777850, 2024). "Recent studies with oral A. soehngenii administration showed that this is safe and that the fecal A. soehngenii abundance is positively correlated with peripheral insulin sensitivity in subjects with metabolic syndrome." (PMID 38542455, 2024). "They showed an even stronger relation between endothelial dysfunction and clustered metabolic syndrome components, especially under a condition with low insulin sensitivity." (PMID 38391741, 2024). "The “metaflammation” concept reflects the crosstalk between the immune landscape, metabolic pathways, obesity and metabolic syndrome (MetS), resistance to insulin and persistent inflammation." (PMID 38612922, 2024). "Studies have shown that FMT from lean donors significantly improves insulin sensitivity in obese subjects with metabolic syndrome." (PMID 38317217, 2024). "Previous research has shown that IR not only disrupted insulin signaling in vital intimal cells such as vascular smooth muscle cells and macrophages, but also created a proinflammatory environment and dyslipidemia." (PMID 39044255, 2024).